IL10 (interleukin 10)
Diseases named in the same sentence as IL10 in open-access papers (continued):
Sharing a sentence is not in itself a finding about the gene and the disease.
tumor (continued). "We demonstrated, for the first time, the effectiveness of LV-based elimination of IL-10 from tumor nodule, its effect on the host immune response, as well as the results of its potential application in antitumor therapy." (PMID 29954431, 2018). "Of these, unstimulated leukocyte IL-10 production, heart rate, and gross tumor volume appeared to be the best predictors of which dogs will develop an inflammatory response to CNV-NT." (PMID 29606140, 2018). "This switch can be driven by various cytokines and signals expressed in the TME, which can be provided by either stromal cells or tumor cells, such as IL-10, glucocorticoid hormones, apoptotic cells, and immune complex." (PMID 29872724, 2018). "The IL-10 mediated positive feedback loop between the tumor and the M2-TAMs helps in the rapid proliferation of the tumor sub-populations and the progression of the disease." (PMID 30183728, 2018). "The antiinflammatory factors, including IL-4, IL-10, and IL-13, inIL-33-treated tumor-bearing mice were also significantly increased." (PMID 29950152, 2018). "We further showed the therapeutic potential of Axl scFv by designing a functional Axl synNotch receptor that can produce IL-10 when activated by Axl+ tumor cells." (PMID 29497107, 2018). "In an in vivo setting, we demonstrated Axl CAR in human primary T cells for killing tumor cells and Axl SynNotch receptor for producing IL-10 in an antigen-specific manner." (PMID 29497107, 2018). "By contrast, the M2 subtype is pro-tumorigenic, since it suppresses immunosurveillance by secreting anti-inflammatory cytokines, e.g., TGFβ and IL-10 or by remodeling tumor stroma." (PMID 30158932, 2018). "Hypoxia-induced factors such as VEGF-A, endothelin-2, and interleukin-10 secreted in the tumor environment encourage differentiation towards the M2 phenotype." (PMID 29382395, 2018). "The delay in tumor growth in their experiments was found to result from the inclusion of the anti-IL10 siRNA in the conjugate." (PMID 29893623, 2018). "Macrophage numbers at the tumor site were similar between the sexes, but tumors from female mice had increased IL-10 producing macrophages (p=0.0685), which is characteristic of M2-type macrophages." (PMID 30400822, 2018). "Expressed IL-10 efficiently suppresses the activation of cytotoxic T lymphocytes (CTLs) and natural killer (NK) cells, resulting in the rapid proliferation of tumor cells." (PMID 29329591, 2018). "Different phenotypes of macrophages often present different roles in tumor microenvironment, which are tightly regulated by factors in the tumor microenvironment including interleukin-4, interleukin-10, immunoglobulin etc.." (PMID 29861872, 2018). "IL-10 stimulates the cytotoxicity of CTL and a deficiency of IL-10 can lead to spontaneous tumor development." (PMID 35847834, 2018). "Some of the already identified vaccine-induced suppressive elements present in IL-10+ DC, are common to those operating at the tumor level, allowing the design of new combinatorial vaccination strategies based on drugs currently approved or in development." (PMID 30233565, 2018). "On the other hand, the production of the anti-inflammatory cytokine IL-10 in tumor lysate-pulsed DCs was strongly attenuated following the engulfment of tumor lysate." (PMID 30081891, 2018). "Tumor-derived IL-10 and prostaglandin E2 can independently increase endothelial cell expression of Fas, and tumor derived VEGF-A is dependent on the presence of IL10 or prostaglandin E2 to further increase Fas expression." (PMID 30766539, 2018). "There is little information available about the in vitro effect of IL-6 and IL-10 on the phenotypic behaviour of BC cells in terms of tumour cell migration or adhesion to lymphatic and blood endothelium, which are key steps in the metastatic process." (PMID 29256156, 2018).
tumor (continued). "Although Tregs are associated with tumor development, one study demonstrated that IL-10 from Tregs induced by type I IFN is necessary to negatively regulate Th17 inflammation in the tumor microenvironment." (PMID 29899823, 2018). "And for the first time, we found that blocking of IL-33 or ST2L reduced thetumor size accompany by decreasing serum IL-10 level in CT26 tumor-bearing mice." (PMID 29950152, 2018). "HIF-1α significantly increased the expression of programmed cell death ligand 1 (PD-L1) and the secretion of IL-6, IL-10, and TGFβ1 in MDSCs in tumor bearing mice." (PMID 29682521, 2018). "A case–control study showed that there was significantly lower serum levels of IL-10 in Iranian CRC cases compared with controls which cause an aberrant innate immune reaction and tumor cell ignorance by adaptive immune." (PMID 30579343, 2018). "Firstly, we profiled the transcript levels of major tumor microenvironment cytokines IL-6, IL-10, tumor necrosis factor-α (TNF-α), and transforming growth factor-β (TGF-β) in PC3 cells in both conditions: with ectopically expressed AIRE and AIRE knockdown." (PMID 29795364, 2018). "The results showed that IL-3, IL-6, and IL-10 were differentially expressed in splenocytes from tumor bearing WT mice compared with tumor-bearing IRF-8−/−, naïve WT and naïve IRF-8−/− mice." (PMID 29438283, 2018). "The effect of IL-33 on NK cells was also demonstrated by reduced presence of IFN-γ-expressing NK cells and increased NK cells that expressed IL-10 in tumor-bearing mice." (PMID 30112116, 2018). "Lastly, Comito and co-workers reported that ZA-treatment reduced angiogenesis, inhibited tumour invasion and prevented M2 polarisation of macrophages by decreasing IL10 levels in the TME." (PMID 30577495, 2018). "IL-10 secreted by the tumor maintains chronic inflammation status in the tumor microenvironment and inhibits activation of the adaptive immunity." (PMID 29849947, 2018). "This was paralleled by the enrichment of H3K4me3, an active gene histone mark, at the promoter of Il10 in sorted tumor-infiltrated CD4 T cells and Tregs." (PMID 29462900, 2018). "Tissue slides from sentinel node biopsies and tumor resections from thirty women who underwent sentinel node biopsy with invasive breast cancer resection were dual stained for CD3/IL-10, CD3/IFN-gamma or triple stained for CD3/CD20/CD68." (PMID 30400835, 2018). "Tumours can induce intratumoral macrophages to overexpress and secrete Gas6 by producing interleukin-10 (IL-10) and macrophage colony-stimulating factor (M-CSF) in the microenvironment." (PMID 29386018, 2018). "It is possible that the overall effect of IL-10 depends on the specific tumor type and TME, therefore a targeted therapy directed to IL-10 should carefully consider the possible dual immunosuppressive and immunostimulatory role of this cytokine." (PMID 30154786, 2018). "Their recruitment sustains tumor growth by the induction of IL-10 producing Treg that in turn suppress the activation of tumor specific effector T cells." (PMID 30319638, 2018). "Resultsshowed that the protein levels of IL-4, IL-10, and IL-13 were significantly increased inthe serum of tumor-bearing mice, respectively (Ps < .05)." (PMID 29950152, 2018). "Interleukin-10 (IL-10), as an important immuno-modulator with pleiotropic functions, is produced by multiple cell types including keratinocytes, immunocyte and tumor cells." (PMID 29467923, 2018). "Consistently, Jurkat T cells that were transiently transfected with tTA responsive IL-10 reporter showed a similar result, activating and secreting IL-10 only when co-cultured with Axl+ tumor cells." (PMID 29497107, 2018). "Supernatants from total lung cells derived from tumor bearing mice showed that an increased secretion of IL-10 in STAT1 KO mice compared to wild-type controls." (PMID 30647851, 2018).
tumor (continued). "In contrast, M2 macrophages act as anti-immunogenic cells that express anti-inflammatory cytokines such as IL-10 and TGFβ, which subsequently inhibit the function of effector T cells and favor tumor progression." (PMID 30115069, 2018). "The effect of EC stimulation with IL-6, and IL-10, on tumour–endothelial cell adhesion was investigated in this study." (PMID 29256156, 2018). "Regulatory T cells (Tregs) are a subpopulation of CD4+ CD25+ T lymphocytes that inhibit anti-tumor immunity by promoting immune tolerance through direct suppressive functions on T cells or by secreting immunosuppressive cytokines such as IL-10 and TGF-b." (PMID 29872507, 2018). "Development of inflammation in response to CNV-NT is best predicted by pretreatment unstimulated leukocyte IL-10 production, heart rate, and gross tumor volume." (PMID 29606140, 2018). "In this study, we found that LBP treatment inhibited the increase of CD4+ CD25high Tregs in tumor tissue, as well as the secretion of IL-10 and TGF-β1 in serum." (PMID 29967800, 2018). "Studies have shown that the tumor microenvironment produces high levels of factors such as IL-10 and TGFbeta leading to NK cell dysfunction." (PMID 29342200, 2018). "Macrophages are also reported to enhance secretion of IL-10 by MDSCs and in return MDSCs down-regulate in a contact-dependent manner IL-12 production by macrophages in tumor models." (PMID 30405617, 2018). "But, the level of IL-10, a Th2 cytokine, was significantly higher in the tumor microenvironment of wild type mice that developed invasive SCC, and only relatively low concentrations of IL-4 and IL-13 were detected." (PMID 30112116, 2018). "In general, macrophages that infiltrate tumor tissues are driven by tumor-and T cell-derived cytokines to acquire a polarized M2 phenotype characterized by production of IL-4, IL-13, IL-10, and glucocorticoid hormones." (PMID 30042333, 2018). "Previous studies looking at expression of IL-6 and IL-10 showed similar cytoplasmic expression patterns in tumour cells of the breast and other tumour types." (PMID 29256156, 2018). "Within the tumor environment, regulatory B cells (Bregs) are widely recognized to inhibit immune responses through IL-10 production." (PMID 29568299, 2018). "TRegs inhibit the function of CD8+ T cells via cell-cell contact dependent mechanisms and by secreting inhibitory cytokines, such as IL-10, thereby limiting their tumor killing capacity." (PMID 30687337, 2018). "In fact in a cancer-environment, IL-10 would act like anti-apoptotic and tumor-growth factor, but during exercise it would act like anti-inflammatory cytokine, increasing the cortisol-level and inhibiting TNF-α." (PMID 29732034, 2018). "To date, the IL-10/STAT3 signaling pathway has been reported to play an important part in tumor progression, chemotherapy resistance and the anti-inflammatory response." (PMID 29497350, 2018). "In this study, we observed a downregulation of IL-10 secretion by splenocytes during the early stages of tumor progression (day 14), which subsequently increased." (PMID 30037009, 2018). "For example IL-10, which is reduced in the Apc+/flxLect2−/− mice, has been shown to be a key cytokine which when produced by Treg cells that can reduce tumour burden in the Apc+/min model." (PMID 30559928, 2018). "The excretion of intra-tumor IL-10, TGF-β was notably lower but higher IFN-γ excretion in this combination immunotherapy." (PMID 30359281, 2018). "Many different immune cells can produce IL-10 and during cancer development, this has mainly been considered detrimental for successful eradication of the tumor cells due to IL-10’s immunosuppressive capabilities on DCs and T cells." (PMID 29988341, 2018). "TAMs suppress the anti-tumor immune response via the secretion of anti-inflammatory cytokines, including IL-10, and supply the tumor with growth factors such as EGF and VEGF, which promote primary tumor growth and angiogenesis." (PMID 29805773, 2018).
tumor (continued). "In response to RT, expression of Fas can be induced by tumor cells secreting IL-10, prostaglandin E2, and VEGF-A." (PMID 30766539, 2018). "The augmented CD200 expression not only attenuates antigen-specific Th1 cytokines such as IFNγ and TNFα production but also direct them to acquire Th2 phenotype (expression of IL-4/IL-10 cytokines in viral and tumor pathogenesis)." (PMID 29915577, 2018). "In an experimental animal model, microenvironmental immature dendritic cells coproducing IL-10 and PD-L1 enhanced anti-tumor immune reaction." (PMID 30458835, 2018). "As a result, we observed activation of DC subsets and of infiltrating T cells, reduced IL-10 levels, and specific tumor cell lysis." (PMID 30400822, 2018). "Studies have reported that tumor-derived exosomal miR-214 inhibited the PTEN protein expression level to induce the secretion of IL-10 by Tregs, leading to the host organism immune escape to promote tumor growth." (PMID 29552328, 2018). "For example, certain γδT cell subsets also contribute to tumor progression by facilitating tumor-related inflammation and immunosuppression, with suppressive γδT cells producing IL-10 and TGF-β." (PMID 29482595, 2018). "The pro-tumor macrophages enhance myeloma cell proliferation and survival by secreting IL-6 and IL-10." (PMID 30405034, 2018). "In contrast, IL-10 is an anti-inflammatory cytokine that induces immunosuppressive response which enables the tumor cells to evade the immune control." (PMID 30081891, 2018). "Studies to delineate the role of IL10 on MDSC tumor modulatory pathways especially in the context of Doxorubicin, HIFU and Salmonella combinatorial therapy are currently in works." (PMID 30166607, 2018). "Once the tumor is established, tumor cells secrete cytokines IL-4, IL-10, IL-13 and lactic acid, and along with the presence of CD4+ Th2 cells, cause the polarization of TAMs toward an M2-like phenotype." (PMID 30356656, 2018). "In this context, IL-12 and type I IFNs have been shown to stimulate antitumor properties, while IL-10 and TGF-β have been linked to tumor-promoting properties." (PMID 30233579, 2018). "These treatments can be made robust with respect to pro-tumor immune cell polarization if coupled with antibodies that neutralize IL-4 and IL-10." (PMID 35847834, 2018). "IL-10 is commonly regarded as immunosuppressive, anti-inflammatory, cytokine that favors tumor escape from immune surveillance." (PMID 29361917, 2018). "On the 6th day after we started the triple inoculations of shIL10–3 LVs, the cells isolated from MC38 tumor nodules showed decreased ability to produce IL-10 compared to both untreated and shN-treated controls." (PMID 29954431, 2018). "IL-10 as an anti-inflammatory cytokine is commonly secreted by type 1 regulatory T cells and can be an oncogene or tumor suppressor based on microenvironment condition." (PMID 30579343, 2018). "In the tumor microenvironment, accumulated Treg cells can secrete relative immunosuppressive cytokines such as TGFβ and IL-10, which impair the antigen-presenting function of DCs and the activation of effector T cells." (PMID 30115069, 2018). "Mo-MDSCs also secrete transforming growth factor-β (TGF-β) and interleukin-10 (IL-10), which have direct immunosuppressive effects and induce regulatory T cells, which suppress tumor-specific T cell responses." (PMID 29543758, 2018). "The cells displayed pro-inflammatory (IL-2, IL-8, and TNFα) and anti-inflammatory (IL-4 and IL-10) activities IL-2, IL-4, and IL-8 can promote the proliferation and survival of tumor cells by means of autocrine/paracrine signaling pathways." (PMID 29495627, 2018). "Although a systemic increase in IFN-γ and TNF-α was observed, IL-10 expression increased in the tumor-bearing mice treated with metformin." (PMID 29899823, 2018). "Tumour cell adhesion patterns to both IL-6 and IL-10 stimulated hMEC-1 and hTERT-LEC were unaltered." (PMID 29256156, 2018).
tumor (continued). "ATOR-1015 slightly inhibits the suppressive effect of Tregs and reduces their IL-10 production.ATOR-1015 administered to hOX40KI mice with colon cancer localizes specifically to the tumor via binding to OX40." (PMID 30400822, 2018). "IL-27 produced by DCs is necessary for trafficking of Tregs to locate in tumor, and pulmonary CD1c+ DC-mediated development of Tregs is dependent on IL-27/IL-10/inducible costimulator ligand." (PMID 30483251, 2018). "IL-10 is an immune cytokine secreted from most leukocytes, including macrophages, as well as from tumor cells themselves." (PMID 29382395, 2018). "Among M2 macrophages, tumor-associated macrophages (TAMs) stimulate regulatory T cell differentiation and secrete several factors (e.g., TGF-β, TNF-α and IL-10) to create a favorable environment for tumor growth and immunosuppression promotion." (PMID 29541395, 2018). "Specifically, the authors found that in a lung carcinoma model in nude mice, miR-214 increased the secretion of IL-10 by Tregs and promoted tumor growth." (PMID 30443251, 2018). "It is possible that cytokines produced by tumour xenografts (such as M-CSF, IL-10 and TGF-β) activate macrophages that migrate to the xenograft, and contribute to their polarisation to a pro-angiogenic phenotype." (PMID 30396905, 2018). "Recent studies of Pegilodecakin, a pegylated interleukin-10 (IL-10), have demonstrated that doses greatly exceeding typical endogenous levels can drive a productive tumor specific T cell expansion and response." (PMID 30400835, 2018). "With the expression of IL-10, it also has the pro-tumor phenotype that contributes to the progression of disease by stimulating proliferation and angiogenesis, suppressing the immune system, and protecting against chemotherapy induced apoptosis." (PMID 30405034, 2018). "Best subsets regression was used to evaluate the variables unstimulated leukocyte IL-10 production, leukocyte NK-like activity, heart rate, lymphocyte count, gross tumor volume and [64Cu]ATSM scan SUVMax max for prediction of inflammation." (PMID 29606140, 2018). "Levels of immunosuppressive cytokines, such as TGF-β and IL-10, were significantly reduced in the tumor microenvironment." (PMID 29967612, 2018). "A subset of CLL cells immunophenotypically resembles B-regulatory cells (Bregs) and produce IL-10 and TGFβ that functionally imparts to them tumor-supportive properties." (PMID 30400835, 2018). "TGF-β produced by tumor-associated MDSCs, together with IL-10 and scarcity of arginine expression, has been shown to facilitate the differentiation and expansion of forkhead box P3 (FOXP3)+ Tregs in other tumor types." (PMID 30619286, 2018). "This inefficient cellular profile was accompanied by high expression of the anti-inflammatory cytokines IL10 and TGFβ1, which is compatible with the “N2-like” neutrophil phenotype previously reported in the tumor microenvironment." (PMID 30233581, 2018). "To illuminate how LBP inhibits the production of TGF-β1 and IL-10 in H22 tumor-bearing mice, we then investigated the effects of LBP on TGF-β1 and IL-10 production in H22 cells and RAW264.7 macrophages in vitro." (PMID 29967800, 2018). "It is also able to recruit NK cells to the tumor site, reactivate anergic tumor-infiltrating lymphocytes (TILs), inhibit regulatory T-cells and the secretion of IL-10, IL-4 and trasforming growth factor beta (TGFβ) by tumor associated macrophages." (PMID 28331617, 2017). "MTT assays were performed at different time points to test tumour cell proliferation, and the results showed that neutralization of IL-10 (1.5 μg/ml) attenuated tumour cell proliferation significantly at 48 h, 72 h and 96 h." (PMID 28099146, 2017). "Recent research indicates that in murine splenocyte culture, exosomes from mycoplasma-infected tumor cells induce B cell-dependent IL-10 and suppress T cell activity." (PMID 28642882, 2017).